PIK3CA (phosphatidylinositol-4,5-bisphosphate 3-kinase catalytic subunit alpha)
Diseases named in the same sentence as PIK3CA in open-access papers (continued):
Sharing a sentence is not in itself a finding about the gene and the disease.
tumor (continued). "At this year’s ASCO Annual Meeting, results from cohort A were presented; this cohort comprised 121 patients with centrally confirmed PIK3Ca mutant tumours who had progressed on or after prior treatment including a CDK4/6 inhibitor." (PMID 33520003, 2021). "Quantitative real-time PCR (qRT-PCR) was employed to evaluate the mRNA abundance of PIK3CA in the patient’s skin lesion." (PMID 34074347, 2021). "Mutations in PIK3CA, which encodes the p110a subunit of PI3K, occur in approximately 20% of GCs, however PIK3CA mutations are less frequent in HER2-positive GC, occurring in only 2% of tumours." (PMID 33933113, 2021). "Activating mutations or amplification of one of the protein genes, generally PIK3CA gene, and/or inactivating mutations (PTEN) result in constitutive activation of the pathway, a feature distinguishable in less differentiated tumours." (PMID 34062862, 2021). "For example, gene CREBBP is a known tumor gene, and it does not show a connection with PIK3CA in the normal state, but it can be regulated by PIK3CA in tumor state." (PMID 34335688, 2021). "The mutational profile of the CTNNA1 germline mutated tumour encompassed somatic mutations in RHOA, a specific DGC and PCC‐NOS gene, and in ARID1A and PIK3CA, genes transversally mutated in both DGC and IGC." (PMID 33724653, 2021). "Among the OCCC cases in this study, two had PIK3CA mutations with MAF ≥ 15% in the eutopic endometrial stroma, and both had the same hotspot mutation in the tumor." (PMID 34172890, 2021). "Differential protein expression was examined between wildtype and PIK3CA and/or ERBB mutated tumours." (PMID 33933113, 2021). "PIK3CA and ESR1 mutations can be detected in circulating tumor DNA in up to every third patient with HR+, HER2− MBC." (PMID 34885105, 2021). "Subgroup analyses of KIRC tissue based on gender, tumor grade, and cancer stage indicated downregulation of PIK3CA mRNA expression." (PMID 34367282, 2021). "Therefore, PIK3CA (p.Glu707Lys) could be a germline mutation that confers tumor predisposition." (PMID 34873204, 2021). "In our study, correlation analysis showed that the expression of PIK3CA in tumor tissues was significantly higher than that in normal tissues." (PMID 33987081, 2021). "Herein, we identified that FOXD1‐AS1 is a cytoplasmic lncRNA in GC and it functions as a ceRNA of PIK3CA through competitive binding to miR‐466, a well‐known tumor suppressor in several cancers." (PMID 32460412, 2021). "In the MBC population of the patients, one actionable mutation—PIK3CA, ESR1, ERBB2, or AKT1—was found in ten patients and two in three cases either in the tumor or in the plasma." (PMID 34298704, 2021). "In particular, treatment with taselisib resulted in marked tumor suppression in preclinical studies performed on PIK3CA-mutant xenografts." (PMID 34298731, 2021). "Pretreatment tumor molecular profiling identified multiple alterations including ERBB2 amplification and PIK3CA H1047R mutation." (PMID 34407844, 2021). "Downregulation of SGK3 by both genetic and chemical means significantly diminishes the viability of PIK3CA mutant cancer cells highlighting the importance of this signalling node in tumours with low AKT activation." (PMID 33810522, 2021).
tumor (continued). "In univariate and multivariate analysis, PIK3CA exon 9, and tumor sites were related to stage III patients’ disease relapse (p-value < 0.05 for all), indicating that these variants were independent predictive markers in recurrence." (PMID 33842311, 2021). "PIK3CA status was determined by tumor tissue RT-PCR and led to the inclusion of 341 patients in the PIK3CA-mutant cohort and 231 in the wild-type group." (PMID 34298731, 2021). "Both baseline and longitudinal ctDNA profiling indicate that the T790M subclonal tumours are enriched for PIK3CA alterations, which we demonstrate to confer resistance to osimertinib in vitro that can be partially reversed by PI3K pathway inhibitors." (PMID 33741979, 2021). "PIK3CA expression was elevated in tumor tissues and its expression was negatively regulated by miR1425p expression." (PMID 34680441, 2021). "The tumor 1 (70% tumor content) had following mutations: KRAS p.G13D (allelic fraction (AF) = 35.27%), APC p.R283*(AF = 32.94%) and PIK3CA p.E545K(AF = 4.34%)." (PMID 34600484, 2021). "The most frequently mutated genes are the tumor suppressors PTEN and FBXW7, which are both mutated in 14.9% of cases in PIK3CA mutated cancers and in 5% and 10.6% of cases, respectively, in PIK3CA wild-type cancers." (PMID 33435133, 2021). "Most of these alterations are activating PIK3CA mutations, which result in upregulated PI3K signaling that can promote HNSCC cell growth, tumor progression, invasion, and metastasis." (PMID 34068608, 2021). "In tumor samples from 1144 NSCLC patients, PIK3CA mutations had an incidence of 3.7%, raised to 8.9% if counting only SCC, while in another cohort of 1117 NSCLCs, they were detected in 3.9% of SCCs and 2.7% of adenocarcinomas." (PMID 33807876, 2021). "For positive controls, we chose PIK3CA as an oncogene with hotspot mutations, and PTEN as a tumor suppressor with mutations throughout the gene." (PMID 34581028, 2021). "For the tumor promoter genes SMAD6, TERT, EGFR, and PIK3CA, low levels of expression were associated with better survival, as expected." (PMID 33919332, 2021). "The pan-PI3K inhibitor NVP-BKM120 significantly suppresses PIK3CA-mutant tumor xenograft growth when combined with HER2-targeted therapy." (PMID 33790792, 2021). "Corresponding circulating PIK3CA mutations were identified in 55% of patients with mutations, while no circulating mutations were found among patients with PI3KCA WT tumours." (PMID 34911971, 2021). "Both Patient 001 and 018 have a predicted neoantigen from 533-542 of PIK3CA in their recurrent tumor." (PMID 33796222, 2021). "In fact, in our screening pipeline, we only considered the candidate genes which was up-regulated in tumor tissues and identified one gene (FSCN1) that was associated with prognosis and response to radiotherapy in PIK3CA-altered patients." (PMID 34249689, 2021).
tumor (continued). "Intriguingly, genomic gain in PIK3CA or PIK3CB were associated decreased CD8 T cells, Th1 cell but increased Th2 cells infiltration in multiple tumor types, which was similar to what we observed for PTEN loss." (PMID 33874915, 2021). "Apart from KRAS and PIK3CA, other genes preferentially altered in the right-sided primary tumor sites, such as PRKDC, ERBB3, BCLAF1 and NOTCH1, have been reported to be correlated with poor prognosis or migration in CRC." (PMID 34281583, 2021). "These are diagnosed at early stages, and tumor growth is stepwise and encompasses mutations in KRAS, BRAF, PIK3CA, and PTEN." (PMID 34721577, 2021). "The only tumor (T31) in which different mutations were observed between both areas was a MMRp tumor showing a KRAS mutation in the glandular area and PIK3CA mutation in the solid area." (PMID 33435234, 2021). "PIK3CA was deregulated in only a minority of tumor samples: overexpressed in 18 (3.9%) and underexpressed in 40 (8.7%) cases." (PMID 33669698, 2021). "Our data indicate a benefit of aspirin usage particularly for patients with combined wild-type PIK3CA and mutated-KRAS tumor characteristics." (PMID 34638442, 2021). "Mutations in PIK3CA were only identified in HER2-negative tumours, while ERBB-family mutations were identified in HER2-positive and HER2-negative tumours." (PMID 33933113, 2021). "Our study also reveals that FSCN1 expression is correlated with the expression of YWHAZ, which encodes the 14-3-3ζ protein, and that silencing FSCN1 downregulates YWHAZ only in tumor cells with PIK3CA alterations." (PMID 34249689, 2021). "Activation of the PI3K/Akt/mTOR pathway, through PIK3CA amplifications, PIK3CA/PIK3R1/PIK3R2 mutations and PTEN mutations/loss of function, has also been linked to more aggressive EC tumor behavior." (PMID 34422646, 2021). "The univariate and multivariate analysis revealed that PIK3CA, age, pTNM stage, and tumor grade were independent factors affecting the prognosis of KIRC patients." (PMID 34367282, 2021). "The anti-proliferative, pro-apoptotic and anti-angiogenic effects of BKM120 have been proven in a variety of tumour types, irrespective the PIK3CA status." (PMID 33004905, 2020). "This tumor harbored both an FGFR1 in frame insertion and a PIK3CA E454K mutation detected by RNA sequencing." (PMID 31677015, 2020). "Downregulated PIK3CA mice group (transfected with sh-PIK3CA) had a stronger fluorescence intensity detected in the bladder area, which showed that downregulated PIK3CA mice had a lower tumor cells than sh-Scb mice (transfected with an empty vector)." (PMID 33344221, 2020). "Mutations of HRAS, FGFR3, PIK3CA and TERT were found in 2.9%, 27.2%, 14.9% and 76.7% of tumor samples, respectively." (PMID 33024200, 2020). "In these cases, pathogenic PIK3CA mutations were present in five (27.8%) cases and only one HER2-positive tumor (5.6%) showed a pathogenic PTEN frameshift mutation (c.309del; p.C105fs)." (PMID 33375706, 2020).
tumor (continued). "Cases with PIK3CA VUS mutations (n =1 14) and cases with both alpelisib on- and off-label mutations in the same tumor (n = 115) were excluded from the analysis." (PMID 32983983, 2020). "For instance, it was reported that human cancers with PIK3CA mutations where AKT activity is deficient, SGK3 serves as the main PDPK1 effector to drive tumour cells survival." (PMID 32926495, 2020). "With the exception of tumor 2, all tumor samples showed characteristic mutations of HNSCC including amplification of 3q26.2 (TP63, SOX2, PIK3CA), 5q14.3 (APC), 8q24.3 (PTK2), 8q22.3 (LRP12) as well as loss and/or LOH of 9p21.3 (CDKN2A)." (PMID 32426287, 2020). "Among the baseline characteristics, age, tumor stage, tumor site, MSI-H phenotype, BRAF mutation, and PIK3CA mutation were significantly different across the four clusters and were adjusted in the following survival analysis." (PMID 33163194, 2020). "The CYLD-mutant cohort also showed significantly lower tumor mutational burden (TMB; median 2.6 vs. 5.2 mut/Mb, p < 0.00001) and less frequent alterations in PIK3CA (13% vs. 31%, p = 0.0015)." (PMID 32461623, 2020). "The tumors were subtyped by gene expression profiling and analyzed for hotspot mutations in FGFR3, PIK3CA and TERT, the most frequent early driver mutations in this tumor type." (PMID 31609466, 2020). "The molecular characterisation of CTCs to assess KRAS, BRAF and PIK3CA status has been achieved, which showed discordance of their status between the primary tumour and CTCs." (PMID 33209110, 2020). "It has been well established that PIK3CA can regulate tumor growth and progression through the PI3K pathway." (PMID 33344221, 2020). "Consistent with the previous findings in PDC models, cytotoxic activity of AZD5363 was the most significant in PIK3CA-E542K-mutant tumor cells." (PMID 32070411, 2020). "Consistent with the results of Ki67, sh-PIK3CA mice tumor issue had lower PIK3CA positive tumor cells than sh-Scb mice." (PMID 33344221, 2020). "After the induction of tumor formation, silencing of PIK3CA-H1047R by the withdrawal of deoxycycline induced complete tumor regression in 1/3 mice, partial regression in 2/3 mice, followed by tumor relapse." (PMID 32210163, 2020). "The amplification of genes encoding PIK3CA and PRKCI was observed in 15% of these tumors, suggesting the activation of the PI3K pathway, one of the most recognized sources of human tumor pathogenesis." (PMID 32899449, 2020). "Although the concordance between matched ctDNA and archival tumor tissue was high for selected ‘hot-spot’ mutations (KRAS, BRAF, PIK3CA), some differences were noted between archival tumor and ctDNA." (PMID 32010431, 2020). "Given the clinical benefit of the PI3Ki alpelisib in patients with PIK3CA mutant HR+/HER2– mBC, determination of tumor PIK3CA mutation status is of importance in managing patients with HR+/HER2– mBC." (PMID 32637176, 2020).
tumor (continued). "PIK3CA profiling showed high clinical specificity and sensitivity in using plasma and urine specimens compared with tumor tissues." (PMID 33044511, 2020). "The distribution of PIK3CA-activating mutations is different in head and neck cancers, with exclusively helical domain C-to-T transitions observed in HPV-positive tumours and a combination of helical domain and kinase domain mutations in HPV-negative tumours." (PMID 33292100, 2020). "In particular, in patients with PIK3CA mutated CRC, the use of aspirin was associated with a reduction of tumor specific and overall mortality of 82% and 46%, respectively." (PMID 36046264, 2020). "In Case 2, the curve of p.E545K PIK3CA in EFIRM revealed a reverse relationship to that of tumor volume (R = -0.65, P = 0.01)." (PMID 32793495, 2020). "PIK3CA locates on chromosome 3 and encodes the p110α catalytic subunit of PI3K, which can enhance cell activity and tumour formation via positively regulating PI3K/Akt activity." (PMID 32611384, 2020). "Activating mutations of oncogenes (PIK3CA, AKT, mTOR) or inactivating mutations of tumor suppressor genes (INPP4B, PTEN) are associated with tumor growth and treatment resistance." (PMID 32276534, 2020). "In one study, AZD5363 showed anti-tumour activity in 50% of patients with PIK3CA-mutant tumours, however, the magnitude of the effects was not significant enough to warrant further monotherapy testing." (PMID 32453400, 2020). "These mutations are validated therapeutic targets, and selection for PIK3CA alterations leads to superior anti-tumor activity of PI3K inhibitors (PI3Ki), resulting in tumor stabilization and, in some cases, regression." (PMID 33036331, 2020). "In combination with our previous report and present results, we showed that overexpression of PIK3CA enriches CSCs both in the primary tumor tissues of PIK3CA mice and in the cell lines derived from these tumors." (PMID 31600013, 2020). "SNVs present with allele frequency of ≤ 5% (rare SNVs) occur frequently in genes commonly mutated during cancer (for example, EGFR, KRAS, PIK3CA, and BRAF), and can provide insight into the dynamics of subclonal tumour populations." (PMID 32024475, 2020). "Compared with sh-Scb mice tumor issue, the ratio of tumor cell with positive Ki67(proliferation related biomarker) was lower in sh-PIK3CA mice." (PMID 33344221, 2020).